Y_RNA (Y RNA )
Gene: Miscellaneous RNA gene on chromosome 2 (236,153,071 to 236,153,172, reverse strand). Ensembl gene ENSG00000207049.
Homologues: Orthologues: chimpanzee Y_RNA (99% identical), macaque Y_RNA (95% identical). Paralogues in human: Y_RNA (88% identical), RNY3 (87% identical), Y_RNA (87% identical), RNY3P1 (86% identical), Y_RNA (86% identical), Y_RNA (85% identical), RNY3P14 (84% identical), Y_RNA (84% identical), Y_RNA (83% identical), RNY3P11 (82% identical), RNY3P16 (82% identical), Y_RNA (82% identical), and 95 more.